ZNF471 (zinc finger protein 471)
Diseases named in the same sentence as ZNF471 in open-access papers (continued):
Sharing a sentence is not in itself a finding about the gene and the disease.
tumor (continued). "We also showed that ZNF471 exerted its tumor-suppressive functions through AKT/GSK-3β and Wnt/β-catenin signaling pathways." (PMID 33203470, 2020). "We also found that ZNF471 exerted its tumor-suppressive functions through suppressing epithelial-mesenchymal transition, tumor cell stemness and AKT and Wnt/β-catenin signaling." (PMID 33203470, 2020). "Next, through The Cancer Genome Atlas (TCGA) Research Network, the relationships between ZNF471 methylation and patient clinicopathological features were analyzed, including sex, age, tumor stage, tumor size, lymph node metastasis, and tumor differentiation." (PMID 32089740, 2020). "ZNF471 methylation was detected in 92/147 (62.6%) tumors but only 22/89 (24.7%) paired adjacent non-tumor tissue samples, and 0/3 (0%) normal esophageal tissues, thus suggesting that ZNF471 methylation is a common event in ESCC." (PMID 32089740, 2020). "Immunohistochemistry (IHC) and hematoxylin and eosin staining were carried out to analyze ZNF471 expression and tumor features of the xenografts in nude mice." (PMID 32089740, 2020). "Collectively, these results suggested that the tumor-suppressive effects of ZNF471 on cell proliferation, migration, and invasion are associated with the transcriptional suppression of its downstream target TFAP2A and PLS3." (PMID 29610526, 2018). "The tumor-suppressive function of ZNF471 was mediated by directly inhibiting its downstream targets TFAP2A and PLS3 transcription." (PMID 29610526, 2018). "In summary, ZNF471 could act as an important tumour suppressor in RCC and is often inactivated by promoter CpG hypermethylation." (PMID 38169650, 2024). "The retroviral mediated overexpression of ZNF471 in SiHa and CaSki cells inhibited growth, proliferation, cell migration, invasion; delayed cell cycle progression in vitro by increasing cell doubling time; and reduced tumor growth in vivo in nude mice." (PMID 33566221, 2021). "We identified ZNF471 as a novel potential tumor suppressor gene in CC that inhibits cancer cell growth, proliferation, invasion, and metastasis by arresting cell cycle progression and induction of EMT by up-regulation of CDH1 and downregulation of CDH2, VIM, and TW1." (PMID 33566221, 2021). "These knockdown results confirmed that ZNF471 functions as a tumor suppressor in ESCC cells." (PMID 32089740, 2020). "Further knockdown of ZNF471 verified its tumor-suppressive effects." (PMID 33203470, 2020). "The direct upregulation of MAPK10/JNK3 expression and activation of downstream proapoptotic targets may be an important mechanism of the tumor suppression of ZNF471 in ESCC cells." (PMID 32089740, 2020). "In vivo, ZNF471 also inhibited the formation of tumor xenografts in nude mice." (PMID 33203470, 2020). "Consistently, we also validate ZNF471 as a tumor suppressor in NSCLC." (PMID 32489316, 2020). "Thus, identifying the target genes regulated by ZNF471 will be important for understanding the molecular basis of its tumor-suppressive effect." (PMID 29610526, 2018). "Moreover, in the subcutaneous xenograft mice model, stable overexpression of ZNF471 in BGC823 cells suppressed tumor growth and volume." (PMID 29610526, 2018). "Thus, ZNF471 CpG specific promoter methylation may determine the prognosis of CC and could function as a potential tumor suppressor by targeting EMT signaling." (PMID 33566221, 2021). "Thus, our data strongly suggest that ZNF471 might act as a tumor suppressor by inhibiting the genes involved in proliferation, growth, migration, and invasion." (PMID 33566221, 2021). "The tumor-specific promoter methylation of ZNF471 may be a candidate biomarker for ESCC diagnosis." (PMID 32089740, 2020). "Under the DNA methylation and gene silencing, Hypermethylation of tumour suppressor genes such as DAPK1, LRPPRC, and ZNF471 were reported." (PMID 41487403, 2026).
tumor (continued). "Zinc-finger protein 471 (ZNF471) exerts its tumor-suppressive functions by suppressing EMT, tumor cell stemness, and the inhibition of Wnt/β-catenin signaling." (PMID 38279330, 2024). "Methylation of ZNF471 promoter of SIL (LSIL and HSIL) at specific CpG sites (positions: 6, 7, and 15 to 19) was also different from normal and tumor tissues." (PMID 33566221, 2021). "Analysis of the public datasets revealed that the ZNF471 gene promoter is significantly hypermethylated in SIL and tumor tissues when compared with normal samples." (PMID 33566221, 2021). "We show that ZNF471 acts as a potential tumor suppressor by regulating epithelial-mesenchymal transition (EMT), and methylation of specific CpG sites occurs within ZNF471 promoter in different tumors and their grades." (PMID 33566221, 2021). "Restoration of ZNF471 expression in silenced ESCC cells significantly altered cell morphology, induced apoptosis and G0/G1 arrest, and inhibited tumor cell colony formation, viability, migration and invasion." (PMID 32089740, 2020). "Of the promoters gaining methylation in our sample, many have already been shown to have tumour suppressor activity, including RORa, FAN1, PRDM1, CYGB, L3MBTL4, EPB41L3, with ZNF471 and ZNF671 being specifically silenced by methylation." (PMID 31357948, 2019). "ZNF471 modulated EMT and functioned as methylation regulated tumor suppressor in cervical cancer." (PMID 38169650, 2024). "These aspects may be related to the observed inhibitory effects of ZNF471 on AKT and Wnt/β-catenin pathways that influence tumor growth." (PMID 37492743, 2023). "Further, expression analysis of ZNF471 along with one epithelial and 9 mesenchymal markers in the GSE9750 dataset identified the downregulation of ZNF471 and CDH1 with concomitant up-regulation of ZEB1 and TWIST1 in tumor tissues when compared with normal samples (P<0.05)." (PMID 33566221, 2021). "To assess its tumor suppressive functions, we transfected pcDNA3.1- ZNF471-Flag-V5-expressing plasmid into ESCC cell lines KYSE150 and KYSE410 with silenced expression of ZNF471." (PMID 32089740, 2020). "On the one hand, the high expression level and CpG hypermethylation of ZNF471 in RCC are likely to be considered potential molecular markers in the future, which might assist pathologists in determining the clinicopathological characteristics of tumours and predicting prognosis." (PMID 38169650, 2024).
cancer (11 papers, 2014 to 2023). A tumor composed of atypical neoplastic, often pleomorphic cells that invade other tissues. "The ZNF471 promoter region occurs frequently methylated in various cancer tissues, including colorectal, tongue squamous cell, breast, gastric, and esophageal cancer." (PMID 33672287, 2021). "We further found that ZNF471 is significantly downregulated in ESCC tissues compared with adjacent non-cancer tissues, due to its aberrant promoter CpG methylation, and further confirmed by methylation analysis and treatment with demethylation agent." (PMID 32089740, 2020). "Frequent methylation of ZNF471 in cancer has also been supported by published epigenetic analysis on colorectal and squamous cell carcinoma." (PMID 29610526, 2018). "Reciprocally we can observe promoter elements being extinguished in cancer cells as exemplified for ZNF471 and ZFP28 (bottom)." (PMID 28859074, 2017). "Besides, we have identified co-methylation of specific CpG sites of ZNF471 promoter in CC, which can be used for distinguishing between cancers as well as different stages within a given cancer." (PMID 33566221, 2021). "As the EMT is closely related to cancer cell stemness, we next verified whether ZNF471 affects cell stemness." (PMID 33203470, 2020). "However ZNF471 behaves in the opposite manner and is expressed at lower levels in cancer cells compared to matched normal tissue." (PMID 28859074, 2017). "Collectively, ZNF471 was a negative regulator of AKT and Wnt/β-catenin pathways and exerted its anti-cancer effect by inhibiting the activation of AKT and Wnt/β-catenin signaling." (PMID 33203470, 2020).
ZNF471 also shares sentences with these, for which no sentence is quoted: Ductal Breast Carcinoma (1 paper); gestational choriocarcinoma (1); invasive breast carcinoma (1); invasive lobular breast carcinoma (1); lung carcinoma (1); squamous cell carcinoma of the (1).